MIR632 (microRNA 632)
Synonyms: hsa-mir-632; MIRN632
Gene: MicroRNA gene on chromosome 17 (32,350,109 to 32,350,202, forward strand). Ensembl gene ENSG00000283774.
Gene Ontology:
Biological process: miRNA-mediated post-transcriptional gene silencing
Cellular component: RISC complex